TFRC (transferrin receptor)
Diseases named in the same sentence as TFRC in open-access papers (continued):
Sharing a sentence is not in itself a finding about the gene and the disease.
iron deficiency (continued). "Despite prolonged exposure to chronic iron deficiency, cells retained viability as well as normal hypoxic responses with significant increases in transferrin receptor and protein accumulation of hypoxia inducible factor 1α." (PMID 34532614, 2021). "Iron deficiency was 7.1%, based on calculated total body iron values from transferrin receptor and ferritin concentrations." (PMID 33802295, 2021). "TFRC mediates iron uptake in the placenta, and iron deficiency during pregnancy increases the risk of PTB24." (PMID 33504832, 2021). "Here, serum soluble transferrin receptor provides a valuable addition to existing methods, although it is known to be a less specific indicator for iron deficiency than ferritin." (PMID 34066446, 2021). "Consistent with iron deficiency and hypoxia, TFRC mRNA increased in parallel with increasing concentrations of DFO compared with controls." (PMID 34532614, 2021). "We used the expression of transferrin receptor 1 (TfR1) as a marker indexing cellular iron deficiency." (PMID 33430126, 2021). "Specifically, in order to better understand the effect of iron deficiency on hippocampal development, a reversible, dominant negative transferrin receptor-1 (DNTfR1) transgenic mouse model was created." (PMID 34439901, 2021). "Iron deficiency decreased from 21.74% to 7.89% (by serum ferritin) and iron deficiency decreased from 66.81 to 38.27% (by soluble transferrin receptor)." (PMID 34201821, 2021). "Various combinations of iron markers, such as ferritin, TSAT or the soluble transferrin receptor are commonly used to define iron deficiency." (PMID 34753505, 2021). "Soluble transferrin receptor (sTfR) concentrations are relative to the cellular iron demand, and raised levels are indicative of iron deficiency." (PMID 34827701, 2021). "In a report, it was stated that soluble transferrin receptor (sTfR) concentration in serum was useful for diagnosis of iron deficiency, especially in a state when one is compromised by inflammatory condition; however, the report did not include pregnant women." (PMID 33101731, 2020). "Treatment of murine RAW 264.7 macrophages with nanoencapsulated DFO promoted an increased expression of transferrin receptor 1 (TfR1) mRNA, a typical homeostatic response to iron deficiency." (PMID 32156022, 2020). "One working definition of iron deficiency is ferritin <12 μg/L or transferrin saturation <16% or soluble transferrin receptor >28.1 nmol/L.15 25 By this definition, 10% of our participants were iron-deficient." (PMID 32565444, 2020). "Irp2 post-transcriptionally regulates the iron-uptake protein transferrin receptor 1 (TfR1) and the iron-storage protein ferritin, and dysregulation of these proteins due to Irp2 loss causes functional iron deficiency in β cells." (PMID 31941883, 2020). "In children with anaemia, rates of iron deficiency (low ferritin based on inflammation status, and/or high soluble transferrin receptor, ≥1.97 mg/L) and zinc deficiency (serum zinc <65 μg/dl) were 81.1% and 53.7%, respectively." (PMID 31595712, 2020). "An alternative marker of iron deficiency is the level of soluble transferrin receptor (sTfR) in serum." (PMID 32481481, 2020). "Studies of the use of soluble transferrin receptor to detect iron deficiency in adult patients with CKD have shown variable results, but in general, it was found to be an inferior marker to cellular measures such as %HRC or CHr." (PMID 29666917, 2019). "In combination with measures of iron status (i.e., transferrin receptor and ferritin), they found that semi-settled women had both higher iron-deficiency anemia and anemia of inflammation compared to settled women." (PMID 30854553, 2019). "The American Academy of Pediatrics (AAP) recommends soluble transferrin receptor (sTfR) as a promising approach to screen for iron deficiency." (PMID 30885726, 2019).
iron deficiency (continued). "Iron deficiency through a knockout of iron import proteins like transferrin receptor (Tfrc) or Dmt1 (Slc11a2) causes anaemia and embryonic or early postnatal lethality in mice." (PMID 31015568, 2019). "The soluble transferrin receptor (sTfR), an early and sensitive biomarker for diagnosing iron deficiency, is particularly useful for identification of concomitant iron deficiency in patients with inflammation." (PMID 31183575, 2019). "Placental expression of the transferrin receptor was also increased in conditions of iron deficiency." (PMID 31752878, 2019). "Iron deficiency prevalence defined using a soluble transferrin receptor threshold of greater than 4·4 mg/L showed a very similar pattern, with the prevalence of iron-deficiency anaemia also higher in both screen-and-treat groups at day 84 (appendix pp 17–19)." (PMID 31607468, 2019). "TFRC plays a pivotal role in iron cellular uptake, and cellular iron deficiency inhibits cell growth and leads to cell death." (PMID 30782157, 2019). "As TFRC mRNA has a 3’ iron responsive element, its transcript levels are expected to increase upon iron deficiency." (PMID 31793879, 2019). "Transferrin and soluble serum transferrin receptor (sTfR), considered early indicators of functional iron deficiency, are related to iron transport and their concentrations are increased with iron depletion." (PMID 31357549, 2019). "Iron deficiency (as determined by soluble transferrin receptor) was present in 46% of patients with scleroderma-PH compared to 16% of patients with scleroderma but no PH (note that not all of these had PAH)." (PMID 29904352, 2018). "In younger adolescents (age < 16 years), median transferrin receptor concentrations were significantly higher and SF and serum iron concentrations were significantly lower, suggesting higher cellular iron deficiency." (PMID 30373264, 2018). "Increased soluble transferrin receptor concentration distinguishes reliably between iron deficiency and ACD." (PMID 30544934, 2018). "While reduced MCV is relatively specific for iron deficiency, its sensitivity is lower than, e.g., that of serum transferrin receptor, especially in the presence of chronic diseases such as CRC40." (PMID 29348549, 2018). "Iron deficiency was defined as hepcidin < 20 ng/l, ferritin < 100 ng/l or soluble transferrin receptor (sTfR)/log(ferritin) > 0.8, measured in blood drawn at intensive care unit discharge." (PMID 30463596, 2018). "The use of soluble transferrin receptor levels allowed us to more accurately define true iron deficiency." (PMID 30314455, 2018). "Deficiency of IRP2 increases the expression of the iron storage protein ferritin and reduces the expression of the transferrin receptor leading to functional iron deficiency and therefore neuronal death." (PMID 28193224, 2017). "This is likely to induce a phenotype of functional iron deficiency, partly explaining the upregulation of transferrin receptor (TfR), an iron uptake protein, in α-syn over-expressing cells, further increasing the cellular iron load." (PMID 28993630, 2017). "Our study also highlights that reference ranges for serum transferrin receptor in specific populations need to validated to support its use alongside serum ferritin in assessing the prevalence and severity of iron deficiency at the population level." (PMID 29155855, 2017). "Iron deficiency was sufficiently severe to cause cellular iron deficiency, indicated by a raised serum transferrin receptor as well as low ferritin, in about 1 in 6 females and 1 in 17 males." (PMID 29155855, 2017). "The transferrin receptor protein is involved in the transport of iron into cells, it is required for erythrocyte development, and it is associated with diseases such as iron deficiency, anemia, and chronic disease in general." (PMID 28784116, 2017). "Iron depletion (serum ferritin <15ug/ml) occurred in 19.2% and cellular iron deficiency (low serum ferritin and transferrin receptor >28.1 nmol/l) in 11.6% students." (PMID 29155855, 2017).
iron deficiency (continued). "To investigate this, we measured serum levels of soluble transferrin receptor 1 (sTfr1), a clinical marker of both stimulated erythropoiesis and functional iron deficiency." (PMID 28135344, 2017). "Using both serum transferrin receptor (sTrf > 8.3 mg/L) and corrected serum ferritin (SF < 30 μg/L) as indicators of iron deficiency, only two children met this criteria (Control = 1; MD = 1) at baseline." (PMID 28895887, 2017). "According to the WHO recommendation, our population of students should be classified as “iron deficiency is prevalent; inflammation is prevalent” based on the prevalence of low serum ferritin <20% and high serum transferrin receptor >10%." (PMID 29155855, 2017). "The higher ferritin levels at higher altitude suggesting greater iron stores contrast with the higher serum transferrin receptor levels suggesting greater cellular iron deficiency." (PMID 29155855, 2017). "Reticulocyte hemoglobin content has a high sensitivity and specificity in the diagnosis of iron deficiency anemia, and its comprehensive diagnostic efficacy is better than other traditional indicators—such as serum ferritin and serum transferrin receptor." (PMID 28468320, 2017). "The ratio of concentrations of soluble transferrin receptor/log ferritin has been suggested as a marker of body iron content but its use to detect iron deficiency remains problematic for reasons discussed elsewhere." (PMID 28770094, 2017). "The total analytical error of a photonic crystal (PC) biosensor in the determination of ferritin and soluble transferrin receptor (sTfR) as biomarkers of iron deficiency anemia in chronic kidney disease (CKD) patients was evaluated against certified ELISAs." (PMID 28946680, 2017). "Iron deficiency, based on plasma ferritin and soluble transferrin receptor concentrations were found in only 13%–14% of the subjects (children and women)." (PMID 25954900, 2015). "Transferrin receptor increases during iron deficiency as the body's tissues attempt to increase intercellular iron concentration, and can be used to distinguish iron deficiency anemia from other forms of anemia even when inflammation is present." (PMID 25375360, 2014). "Though less affected by inflammation than SF or Tfs, soluble transferrin receptor (sTfR) levels begin to change relatively late in iron deficiency; further, levels can also be affected by other causes of altered rates of red blood cell generation." (PMID 25310252, 2014). "Both in univariate analysis and in parsimonious models obtained by multivariate analysis, whole blood and erythrocyte ZPP were associated with iron deficiency, anaemia, and plasma concentrations of soluble transferrin receptor." (PMID 25428714, 2014). "The use of the soluble transferrin receptor assay has considerable potential in the routine assessment of iron deficiency and there is a need for additional studies addressing the overall cost effectiveness of this assay in different clinical settings." (PMID 24244281, 2013). "In T. brucei, the transcripts for the transferrin receptor (ESAG6/7) are rapidly upregulated in response to iron deficiency." (PMID 23750752, 2013). "Soluble transferrin receptor (sTfR), a transmembrane protein expressed abundantly on erythroid precursors in the bone marrow, is of value in identifying iron deficiency." (PMID 24244281, 2013). "In the context of iron deficiency, the findings also highlight the impact of using the soluble transferrin receptor assay in addition to serum ferritin on the estimated prevalence of iron deficiency." (PMID 24244281, 2013). "Future studies on the potential impact of host iron deficiency in TB progression should aim to use multiple markers of iron deficiency, including those less influenced by the acute phase response such as soluble transferrin receptor." (PMID 22606361, 2012). "At day 21.5 of gestation, placental and maternal liver transferrin receptor (TfR) expression was increased with iron-deficiency." (PMID 23110188, 2012).
iron deficiency (continued). "The soluble transferrin receptor (sTfR) is a diagnostic tool for differentiating between iron deficiency anemia (IDA) and anemia of chronic disease since ferritin levels reflect amounts of stored iron while the sTfR reflects the functional iron compartment." (PMID 22523639, 2012). "When IRE-binding activity is diminished by genetic loss of Irps, expression of an iron importer, transferrin receptor 1 (TfR1), decreases and expression of the iron storage protein, ferritin, increases, and these changes can cause functional iron deficiency." (PMID 22003390, 2011). "In the same survey 23% of people had elevated transferrin receptor (TfR) levels that were indicative of iron deficiency." (PMID 20195369, 2010). "In iron-deficiency anemia patients, soluble transferrin receptor determinations were higher than in heterozygous beta-thalassemia, but an overlap between the two groups was observed." (PMID 12870058, 2003). "Soluble transferrin receptor values of more than 23 nmol/liter showed 100% sensitivity for recognizing iron-deficiency anemia patients, but only 69.4% specificity." (PMID 12870058, 2003). "Soluble transferrin receptor presented better accuracy (87.6%) than high-fluorescence reticulocytes (54.1%) for distinguishing iron-deficiency anemia from heterozygous beta-thalassemia." (PMID 12870058, 2003). "The correlation between high-fluorescence reticulocytes and soluble transferrin receptor was weak and only reached significance (p = 0.025, r = 0.349) in the iron-deficiency anemia group." (PMID 12870058, 2003). "High-fluorescence reticulocyte counts and soluble transferrin receptor levels were determined in iron-deficiency anemia patients (n = 49) and heterozygous beta-thalassemia patients (n = 43)." (PMID 12870058, 2003). "Transcriptomic analysis (RNA-seq) revealed that PVD significantly reshaped the gene expression profile of HUVECs, characterized by a marked upregulation of iron homeostasis-related genes, such as TFRC, indicating a state of apparent intracellular iron deficiency." (PMID 42077440, 2026). "CD71, also known as the transferrin receptor, may influence the function and differentiation of immune cells in iron deficiency." (PMID 40218909, 2025). "Additionally, based on the upregulation of cell surface transferrin receptors (TfR) due to iron deficiency mechanisms, we successfully developed uniform Tf-modified doxorubicin liposomes (Tf-LPD)." (PMID 40723232, 2025). "Notably, iron supplementation rescues CAL27 cells from Cd-induced damage, while exacerbating iron deficiency through transferrin receptor CD71 silencing amplifies cytotoxicity." (PMID 40612671, 2025). "Previous studies have shown that INF-γ can induce the iron deficiency pathway by upregulating the expression of divalent metal ion transporter 1 in monocyte macrophages and downregulating the transferrin receptor of infected cells and ferrous transporter in monocyte macrophages." (PMID 40236451, 2025). "Physiologically based ferritin thresholds for iron deficiency in conjunction with other blood markers (such as transferrin saturation, soluble transferrin receptor, hepcidin concentration, and haemoglobin concentration) would allow for better informed research." (PMID 39010146, 2024). "Notably, transferrin receptor 1 (TfR1) is highly expressed on the surface of bone marrow progenitors in cases of iron deficiency, particularly on specific progenitors like the common lymphoid progenitor." (PMID 39452542, 2024). "Accordingly, ferritin is considered the best indicator for iron deficiency in adults, and serum ferritin combined with blood hemoglobin (Hb) level, soluble transferrin receptor, and transferrin saturation are the most used tests to detect IDA and iron deficiency." (PMID 37440537, 2023).
iron deficiency (continued). "Because TFRC is indispensable for cellular iron uptake, and considering the essential role of Fe‐S clusters for mitochondrial respiration, it is reasonable to postulate that an iron deficiency damaged mitochondrial thermogenesis function." (PMID 37646182, 2023). "Finally, secondary outcomes such as serum ferritin, serum transferrin receptor, and transferrin saturation indicate a long-standing and sustained parameter of storage iron, and their depletion can result in iron deficiency." (PMID 37069552, 2023). "Mice with skeletal-muscle specific deletion of the transferrin receptor, and thus iron deficiency in muscle, had impaired skeletal muscle metabolism but also developed a severe and lethal systemic metabolic phenotype with disappearance of fat pads and development of hepatic steatosis." (PMID 37029208, 2023). "Furthermore, serum ferritin, serum transferrin receptor, and transferrin saturation have been shown to be more accurate indicators of iron deficiency anemia." (PMID 37069552, 2023). "The soluble transferrin receptor (sTfR) was the best parameter in assessing iron deficiency in CF." (PMID 36771186, 2023). "Thus, PANK2 silencing by siRNA in several human cell lines leads to a reduced proliferation rate accompanied by a paradoxical iron deficiency and increased Transferrin receptor protein 1 (TfR1) expression levels." (PMID 37895830, 2023). "Serum sTfR generally represents a constant proportion of the total mass of the tissue transferrin receptor; however, the proportion increases in case of iron deficiency, which could potentially affect our associations." (PMID 37513632, 2023). "Iron deficiency was defined as soluble transferrin receptor (sTfR) > 28.1 nmol/L." (PMID 35304704, 2022). "The increased transferrin saturation with nearly unchanged levels of soluble transferrin receptor could indicate a disturbed iron metabolism resulting in iron deficiency and in turn in reduced complex I activity." (PMID 36303924, 2022). "The concomitant decrease in the level of iron in the brain can be determined by directly measuring the iron content or indirectly, as here documented, by analyzing the density or expression of the transferrin receptor, (TrfR), which is specifically upregulated with chronic cellular iron deficiency." (PMID 35268590, 2022). "In contrast, soluble transferrin receptor (sTFR) reflects the bone marrow’s demand for iron and therefore, increases iron deficiency, in contrast to ferritin, its fluctuations over the course of the day are smaller and exercise-induced changes are also more reliably indicated by sTFR." (PMID 36364775, 2022). "The transferrin receptor plays a critical role in iron metabolism by precisely controlling the flow of transferrin iron into body cells and reflects the total body mass of tissue receptors, which rise significantly in serum with tissue iron deficiency." (PMID 35405659, 2022). "Iron deficiency is associated with the overexpression of the transferrin receptor on the cell surface and, consequently, with an increase in the serum concentration of the soluble transferrin receptor (RsTf)." (PMID 35956390, 2022). "Furthermore, using hemoglobin < 11.0 g/dL as a proxy indicator, the SEANUTS study found a prevalence of iron deficiency anemia between 9.0% and 18.4%, whereas using soluble transferrin receptor as an indicator revealed a prevalence between 32.3% and 38.9%." (PMID 35609881, 2022). "A high level of soluble transferrin receptor (sTfR) may be a reliable indicator of iron deficiency anemia in hospitalised burn patients." (PMID 36296932, 2022). "In patients influenced by inflammatory or infectious diseases, the quantification of SF level can assist the identification of inflammation-related anemia from iron-deficiency anemia by simultaneously considering other indicators of iron deficiency such as soluble transferrin receptor (STfR)." (PMID 36008974, 2022).